IL6 (interleukin 6)
Diseases named in the same sentence as IL6 in open-access papers (continued):
Sharing a sentence is not in itself a finding about the gene and the disease.
viral infection (continued). "Therefore, SMYD2 inhibits the production of IFN-I and proinflammatory cytokines IL-6 and TNF-α in immune cells upon viral infection." (PMID 37673879, 2023). "Nevertheless, seizures could be additionally explained by the more widespread effect of IL-6 and TNF-α produced by macrophages in response to viral infection in the CNS." (PMID 37363223, 2023). "Since SSRIs potently inhibit IL-6 production via TLR3, SSRIs may be effective as therapeutic agents against cytokine storms induced by viral infection." (PMID 35814203, 2022). "No biomarkers or cytokines seemed to have the ability to predict the pathogen category, while BALF IL-6, blood ANC, and ESR may assist in the diagnosis of single MP, bacteria, and virus infections, respectively." (PMID 36160800, 2022). "It was reported that PCV2 can promote the expression of interleukin 6 (IL6), IL8, IL10, pro-inflammatory cytokines, and activate nuclear factor-κB (NF-κB), thus coordinating cellular immune response and inflammatory reaction, and promoting virus infection." (PMID 35457287, 2022). "These phenomena could be due to the fact that DVP-1 strengthened the organic immunity by stimulating the TLR4/MyD88/NF-κB signaling pathway by which more cytokines, such as IL-1β, IL-4, IL-6, and TNF-α, were generated and released before the viral infection." (PMID 36177044, 2022). "In particular, the expression of cytokines IL-1β, IL-6, and TNF-α was higher than that of the regulatory cytokine IL-10, resembling a cytokine profile characteristic of M1 phenotype, which typically intervene in counteracting bacterial and viral infections." (PMID 36016576, 2022). "In order to confirm whether the oral and the SL immunization could suppress the inflammatory response incurred through viral infection, pro-inflammatory cytokines, interferon-gamma (IFN-γ) and interleukin-6 (IL-6), levels were assessed in the lung homogenates." (PMID 35888065, 2022). "In detail, TLR7 favors the production of cytokines involved in CD4+ T helper 17 (Th17) cell polarization (IL-1β, IL-6, and IL-23) after virus infection with MV and VSV, whereas TLR8 promotes the TH1-promoting cytokine response and type I IFN production after viral infection with ECMV." (PMID 36359340, 2022). "The average (n=3) level of IL-6 and IL-8 was increased after S. pneumoniae infection and bacto-viral co-infection, but not after single viral infection." (PMID 35281454, 2022). "Significant changes in creatinine, D-dimers, ferritin, and IL-6 were noted from P1 to P3 compared with those who received chemotherapy 2–6 months prior to virus infection and non-cancer patients." (PMID 35360723, 2022). "CRP is a non-specific acute-phase protein induced by IL-6 in the liver and a marker of inflammation, bacterial or viral infection, and tissue damage." (PMID 35453906, 2022). "Likewise, poliovirus protein 3A inhibits the transport from the endoplasmic reticulum to the Golgi apparatus, blocks TNF-induced apoptosis and even limits IL-6, IL-8 and IFN-β secretion during viral infections." (PMID 35222374, 2022). "Viral infection by SARS-CoV-2 initially activates innate immune cells, thus recruiting them to the sites of infection and producing pro-inflammatory cytokines including IL-6, IL-12, and TNF-α, etc." (PMID 35330839, 2022). "BALF IL-6, CRP, and ESR may help in diagnosing single MP, bacteria, or virus infection, respectively." (PMID 36160800, 2022). "In the attempt to discover the relationship between IL-6, SARS-CoV-2 infection and CD, it can be said that, after the onset of infection, the release of IL-6 as a proinflammatory marker is beneficial in controlling viral infection and bacterial complications." (PMID 35887067, 2022). "Perhaps unsurprisingly, due to the importance of IL-6 in controlling the early stages of viral infections the prophylactic use of anti-IL-6 antibody had no impact on survival of mice infected with wt SFTSV." (PMID 35529317, 2022).
viral infection (continued). "In our study, infection with WT SARS-CoV-2, and Gamma and Zeta variants induced IL-6 and TNF production in nonimmunized mice and variable expression levels according to lineage, reinforcing the different susceptibility of mice to viral infection." (PMID 34960708, 2021). "Finally, to assess the relation of virus infections with inflammation, IFN-α, IFN-β, and IL-6 were among the proinflammatory cytokines used in the study." (PMID 34696175, 2021). "It has been documented that TLRs could activate ADAM17 leading to tumor necrosis factor alpha (TNF-α), interleukin-6 (IL-6) and epidermal growth factor receptor (EGFR) after viral infection." (PMID 33926110, 2021). "Due to the virus infection, MRC-5 cells mainly secrete IL-6, IL-8, and other inflammatory factors, which may be related to the lung inflammation damage during the infection of HAdV." (PMID 34960654, 2021). "As previously reported, IRF1 could be induced by many cytokines such as IFNs (-α, -β, -γ), TNF-α, IL-1, IL-6, LIF and virus infection mediated by STAT and NF-κB." (PMID 34930359, 2021). "Also, we performed ELISA experiments to characterize the change in levels of TREM-1 downstream cytokines, and the results proved that IL-6, IL-8, TNF-α, and others were indeed upregulated in response to viral infection." (PMID 34887856, 2021). "Furthermore, in numerous bacterial and viral infections, including septicemia, pneumonia, influenza, and HIV infection, high IL-6 has predicted worse outcome." (PMID 35062248, 2021). "Viral infections during pregnancy elicit high levels of circulating IFN-γ, TNF-α, IL-6, and TGF-β." (PMID 33430059, 2021). "IL-6 is not permanently produced by normal cells, but its expression is increased by a variety of cytokines, lipopolysaccharides, or viral infections." (PMID 35919677, 2021). "Whereas the downregulation of lncRNA PVT1 seems to protect pancreatic β cells from injury, both up-regulated MALAT1 and NEAT1 had been related to inflammatory mediators (TNF-alpha, IL-6, CXCL10), SLE pathogenesis and innate immune response against viral infections." (PMID 35058920, 2021). "Two other crucial cytokines, IL-6 and TNF-α, which generated in abundance by IL-1β stimulation or autocrined from the activated “mononuclear-macrophage system”, are elevated not only in bacterial infection but also during viral infection." (PMID 34059076, 2021). "The reduction of the inflammatory biomarker IL-6 following inhaled IFN-α2b therapy not only supported a clinically relevant impact of this approach, but also hinted at likely functional connections between viral infection and host end organ damage." (PMID 32574262, 2020). "Furthermore, while certain genes were repressed during both virus infections (e.g., Irf7 or Ifnb1), expression of others was more prominently reduced upon H5N1 infection (e.g., IL-1β, IL-6, Ccl2)." (PMID 32231671, 2020). "Several reports suggest that IL-6 expression is correlated with disease severity following influenza (H1N1) infection and that IL-6 plays an essential role in tissue repair during viral infection." (PMID 32765481, 2020). "With H1N1 infection, human macrophages and neutrophils produced significantly higher levels of pro-inflammatory cytokines and chemokines, such as TNF-α, IL-1β, IL-6, and fractalkine, compared to that with no virus infection." (PMID 32901688, 2020). "IL-6, similarly to IFN-ß, is a cytokine involved in the acute inflammatory response to viral infection and the sIL6R exhibited an extensive antiviral activity against DNA and RNA viruses without IL-6 mediation." (PMID 32244308, 2020). "BBB permeability could increase in response to proinflammatory stimuli such as tumor necrosis factor-α (TNF-α), interleukin-6 (IL-6), and IFN-γ, enabling infiltration of immune effectors into the CNS to clear viral infection." (PMID 32268591, 2020).
viral infection (continued). "Furthermore, inflammatory responses induced by various microbial and viral infections led to the production of pro-inflammatory cytokines such as TNF-α, IL-6, and IL-1β in macrophages via upregulation of the PI3K/AKT and MAPK pathways." (PMID 32867320, 2020). "The leading contribution of MCs in response to viral infection might be in the context of the producing panel of mediators (amines, tryptase, chymase) and cytokines/chemokines (TNF-α, IL-4, IL-5, IL-6, IL-13, and IL-17)." (PMID 32185237, 2020). "In addition to viral infection, EGFR has been documented to play a role in increasing IL-6 expression." (PMID 31470515, 2019). "Similarly, in EV71-infected U251 cells, IL-6-Ab blocked EV71-induced IL-6 production and cell apoptosis in response to viral infection." (PMID 31730654, 2019). "Indeed, the involvement of SOCS3 in the regulation of IL-6 expression was demonstrated by our in vitro and in vivo experiments showing that depletion of SOCS3 significantly reduced the viral infection-triggered expression of IL-6." (PMID 31474976, 2019). "This proposal explains why most tissues collected from PRV-Becker infected mice showed high levels of G-CSF and IL-6 at early time post-infection, independent of a systemic inflammation and evidence of viral infection." (PMID 31675371, 2019). "IL-6 is known to be negative regulators of IFN-γ, in addition IFN-γ suppresses the expression of MARCO in alveolar macrophages inhibiting bacterial clearance in the lung after viral infection." (PMID 32038632, 2019). "Further, the viral particle of baculovirus is able to evoke robust innate immune responses by regulating cytokines such as interleukin 6 (IL-6) and tumor necrosis factor alpha (TNF-α), which may take place in blocking the viral infection." (PMID 29954081, 2018). "We observed that the host-protein signature yielded significantly superior performance for diagnosing bacterial versus viral infections in these patients as compared to the individual biomarkers CRP, PCT, WBC, ANC, IL-6, and HNL, and their currently used combinations." (PMID 29700762, 2018). "While a significant upregulation was detected for IL-6 and IL-1β, The effect was apparently not specific for the virus infection, as it was also evident in the mock-infected co-culture, albeit lower than the influenza-infected group." (PMID 30467502, 2018). "Furthermore, examination of IFN and ISGs mRNA transcripts in cells infected with FMDV S fragment mutant demonstrated an upregulation of Mx-1, IFNβ, IL-6, TNFα, and IRF7 when compared to WT virus infection." (PMID 30483224, 2018). "To explore whether this observation was specific to these 3 donors or an inherent property of the viral strains, we screened MDMs from an additional 16 donors for induction of IL-6 and CCL5 during viral infection." (PMID 28877226, 2017). "The results showed that, after virus infection Brd3 knockout (Brd3-ko) cells showed significantly decreased IFN-β production both in mRNA and protein levels, and, to a much lesser extent, IL-6 production." (PMID 28045112, 2017). "Virus infection leads to a modest increase in secretion of CCL2, IL-6, IL-8, and GM-CSF." (PMID 29228979, 2017). "Our present work reveals that upon the IAV infection, human macrophages produced significantly higher levels of pro‐inflammatory cytokines, such as TNF‐α, IFN‐α, and IL‐6, compared to that with no virus infection." (PMID 28646616, 2017). "IL-6, as well as HBV envelope-specific cytotoxic T lymphocytes (CTL), helps to eliminate viruses by repressing HBV replication and gene transcription in hepatocytes at the early stage of virus infection." (PMID 27434097, 2016). "Patients with high cellularity present elevated levels of cytokines regardless of viral infection except for the levels of IL-6." (PMID 26286516, 2015).
viral infection (continued). "In separate publications a group in Hong Kong reported that elevated levels of IL-6, CXCL8, CCL2, and sTNFR-1 correlated with severe cases of A(H1N1)pdm09 virus infection overall and, in particular, with the extent and severity of influenza-associated pneumonia." (PMID 23468921, 2013). "A similar IL-6 response was observed following co-infection, although the increase appeared to be additive rather than synergistic for some donors since virus infection alone already induced secretion of robust amounts of this cytokine." (PMID 23421931, 2013). "As indicated in the results, the production of IFN-α, IFN-β, IL-1β, IL-6 and TNF-α of PAMs is improved highly after CSFV Shimen strain infection, supposing the cells might use this way to defense the virus infection and to protect the host from harm." (PMID 24034559, 2013). "Addition of anakinra to the medium during and after viral infection completely blocked the release of IL-6 and IL-8 without significantly affecting IP-10 production." (PMID 23723976, 2013). "DHA pretreatment also significantly reduced IL-6 and TNF-α pro-inflammatory cytokine production during both TLR-3 and TLR-7 microglia activation, proving that DHA can exert its anti-inflammatory properties in both types of simulated viral infections." (PMID 23398903, 2013). "For IL-6, serum levels were not detectable in any patient with a viral infection, in any control subjects, and in a minority of patients with a bacterial infection (5 of 21; 23.8%)." (PMID 23690657, 2013). "During the first 1–4 day after virus infection, virus are replicated in cardiac myocytes and trigger innate immune signaling, which contribute to the increasing expression of pro-inflammatory cytokines including TNF-α, IL-6, IL-1β and chemokines." (PMID 23029542, 2012). "In conclusion, PAD4 does not restrict viral replication and does not substantially impact IL-6 production upon viral infection." (PMID 21779371, 2011). "While the mechanism by which viral infection leads to autoimmune myocarditis is not completely understood, there is compelling evidence to suggest that interleukin (IL)-6 is involved." (PMID 19587788, 2009). "In the absence of IL-6, we observed greater severity of chronic myocarditis that correlated with changes in the early immune response to virus infection." (PMID 19587788, 2009). "IL-6, a critical cytokine in immune regulation and inflammation, may enhance host defense against viral infections in non-eosinophilic asthma." (PMID 40599681, 2025). "Chronic inflammation, triggered by bacterial or viral infections or autoimmune processes, generates an environment rich in pro-inflammatory cytokines, such as interleukin-1 beta (IL-1β), tumor necrosis factor-alpha (TNF-α), and interleukin-6 (IL-6), which directly impact cerebral endothelial cells." (PMID 40141084, 2025). "Given the importance of IL-6, TNF-α, IL-12p40, and IL-27 in aiding the immune system during viral infections such as influenza, vaccinia virus, HIV, and herpes simplex and supporting viral immunity, a fermentate that can enhance these cytokines could be beneficial." (PMID 38674902, 2024). "Upon virus infection, AM produce interferons (IFN) to restrict viral replication especially in the early stages of infection as well as other pro-inflammatory cytokines and chemokines such as tumor-necrosis factor α (TNFα), interleukin 6 (IL-6) and interleukin 8 (IL-8)." (PMID 39543713, 2024). "In conclusion, our results show that blockade of IL-6R in hospitalized patients with COVID-19 pneumonia produces only minimal changes in HDL-C levels, suggesting that the viral infection, and not IL-6–mediated inflammation, is the main driver of HDL-C depression." (PMID 38795859, 2024).
viral infection (continued). "In response to viral infections, the generation of a pro-inflammatory response includes the activation of numerous transcription factors, including NF-κB, and the secretion of numerous pro-inflammatory cytokines and metabolites, including TGF-β, IL-1, IL-6, IL-11, and TNF-a." (PMID 36677504, 2023). "However, we detected no further induction of IFN-α after virus infection despite a surge of pro-inflammatory responses (IL-6, IL-1β, TNF-α, IFN-γ CCL2, CCL3, and CXCL10) compared to mature hamsters." (PMID 37122119, 2023). "In an experiment using a MIA rat model, the administration of IL-6 during pregnancy induced ASD-related symptoms in adult offspring, in contrast to the effect observed in offspring of IL-6 knock-out rats injected with poly (I:C) – that mimics a viral infection." (PMID 37305482, 2023). "During bacterial and viral infections, local sensor cells in respiratory tract, including airway epithelia cells, alveolar macrophages and dendritic cells, firstly response to pathogens and secret the first-order cytokines, such as type I and III IFN, IL-6, TNF-α, IL-12, IL-25, IL-33, IL-1β, etc.." (PMID 38029253, 2023). "However, the IL-6 level cannot be used to distinguish between bacterial infection or viral infection, and some noninfectious factors, such as trauma and surgery, can also cause an increase in the IL-6 level." (PMID 38813035, 2023). "Meanwhile, ARND also downregulated the levels of mRNA expression of proinflammatory transcription factors (NF-κB and c-Rel), proinflammatory cytokines (IL-1β, IL-6, TNF-α and CCL2) and NOS2 in vitro, which may be useful to attenuate the inflammatory response upon viral infection." (PMID 35897044, 2022). "In vitro, IFN-β and ISG15 can directly resist viral infections, whereas pro-inflammation cytokines IL-6 and IL-8 may not have antiviral effects on a single cell." (PMID 35418961, 2022). "Furthermore, SARS-CoV-2 infection induces several proinflammatory cytokines such as TNFα, interleukin (IL) -1, and IL-6, and activates the NLR family pyrin domain containing 3 (NLRP3) inflammasome pathway which is important for the host’s defense during viral infection." (PMID 36417106, 2022). "Thus, we have shown that absence of type I IFN signaling during viral infection results in excessive IL-6 production, and that macrophages are crucial for the observed tissue pathology." (PMID 35512020, 2022). "Reports suggest that IL-6 signaling is important for PD-L1 expression after viral infection, but this may not be the case in vitro, as shown in our study." (PMID 34827481, 2021). "Moreover, virus infection enhanced the expressions of TNF-α, IL-1β, IL-6, IL-10, IFN-α, and IFN-β." (PMID 33827620, 2021). "Indeed, while inflammatory cytokine production was negligible (IL-1β, TNFα) or not significantly increased (IL-6), the production of IL-10 and of TNFRs was significantly enhanced upon viral infection." (PMID 34901152, 2021). "Primary SARS-CoV-2 respiratory infection induces systemic inflammation (CXCL10, IFN-ɤ, IL-1B, IL-6, IL-8, IL-17, TNF-α) that can impact the musculoskeletal system through the expression of hACE2-R and TMPRSS2 genes in various types of musculoskeletal cells, allowing direct viral infection." (PMID 33919537, 2021). "Overall, both IL-6 and TNF-α are major contributing factors to the development of cytokine storms as well as neurological and cardiovascular pathologies characteristic of viral infections such as COVID-related medical conditions, and therefore they are important targets for immunomodulatory therapy." (PMID 34502130, 2021). "Indeed, viral infections generally result in lower CRP-responses compared with bacterial infections, and SLE patients rarely mount a CRP-response that corresponds to their inflammatory activity or circulating IL-6 levels." (PMID 33584722, 2020).